ABCG1 (ATP binding cassette subfamily G member 1)
Description:
Catalyzes the efflux of phospholipids such as sphingomyelin, cholesterol and its oxygenated derivatives like 7beta-hydroxycholesterol and this transport is coupled to hydrolysis of ATP. The lipid efflux is ALB-dependent. Is an active component of the macrophage lipid export complex. Could also be involved in intracellular lipid transport processes. The role in cellular lipid homeostasis may not be limited to macrophages. Prevents cell death by transporting cytotoxic 7beta-hydroxycholesterol.
Synonyms: ABC8; WHITE1
Tractability: Small molecule: a structure with a bound ligand is known. Antibody: UniProt places it where antibodies can reach, with high confidence; its Gene Ontology location is reachable by antibodies, with high confidence; UniProt predicts a signal peptide or a membrane-spanning region. PROTAC: ubiquitination databases record sites on it.
Safety:
Unwanted effects reported when the protein is acted on. In parentheses: how it was acted on, where the effect was seen, and who reports it.
Neutropenia (source: ClinPGx)
Gene: Protein-coding gene on chromosome 21 (42,199,689 to 42,304,389, forward strand). Ensembl gene ENSG00000160179.
Subcellular location: Endoplasmic reticulum membrane; Golgi apparatus membrane; Cell membrane
Subcellular location (Human Protein Atlas): Golgi apparatus; Vesicles
Pathways (Reactome):
Transport of small molecules: ABC transporters in lipid homeostasis; HDL remodeling
Signal Transduction: NR1H3 & NR1H2 regulate gene expression linked to cholesterol transport and efflux
Gene Ontology:
Molecular function: ABC-type sterol transporter activity; ADP binding; ATP binding; cholesterol transfer activity; floppase activity; phosphatidylcholine floppase activity; protein binding; protein heterodimerization activity; protein homodimerization activity; toxin transmembrane transporter activity; cholesterol binding; phospholipid binding; ABC-type transporter activity; ATP hydrolysis activity; protein dimerization activity
Biological process: amyloid precursor protein catabolic process; cholesterol efflux; cholesterol homeostasis; cholesterol metabolic process; glycoprotein transport; intracellular cholesterol transport; phospholipid efflux; phospholipid homeostasis; positive regulation of amyloid-beta formation; positive regulation of protein secretion; response to lipid; high-density lipoprotein particle remodeling; low-density lipoprotein particle remodeling; negative regulation of cholesterol storage; negative regulation of macrophage derived foam cell differentiation; positive regulation of cholesterol biosynthetic process; regulation of cholesterol metabolic process; reverse cholesterol transport; xenobiotic detoxification by transmembrane export across the plasma membrane; cellular response to high density lipoprotein particle stimulus; lipid translocation; negative regulation of lipid storage; positive regulation of cholesterol efflux; transmembrane transport
Cellular component: external side of plasma membrane; Golgi apparatus; mitochondrion; plasma membrane; endosome; recycling endosome; endoplasmic reticulum membrane; Golgi membrane; membrane
Genetic constraint (gnomAD): Loss-of-function variants: 27 observed, 64.93 expected, observed/expected ratio (o/e) 0.42, 90% interval 0.31 to 0.57. The upper end of that interval is the gene's LOEUF score, 0.57, which puts it in group 2 of 6, group 1 being the genes least tolerant of losing a copy. Missense variants: 714 observed, 905.77 expected, observed/expected ratio (o/e) 0.79, 90% interval 0.74 to 0.84. Synonymous variants: 368 observed, 383.88 expected, observed/expected ratio (o/e) 0.96, 90% interval 0.88 to 1.04.
Homologues: Orthologues: macaque ABCG1 (98% identical), rat Abcg1 (97% identical), dog ABCG1 (97% identical), mouse Abcg1 (97% identical), pig ABCG1 (96% identical), guinea pig ABCG1 (96% identical), chimpanzee ABCG1 (90% identical), tropical clawed frog abcg1 (87% identical), zebrafish abcg1 (86% identical), Drosophila melanogaster Atet (54% identical), Drosophila melanogaster CG9663 (41% identical), Drosophila melanogaster CG4822 (37% identical), and 8 more. Paralogues in human: ABCG4 (70% identical), ABCG2 (27% identical), ABCG5 (24% identical), ABCG8 (22% identical).
Diseases named in the same sentence as ABCG1 in open-access papers:
ABCG1 is named in the same sentence as 141 diseases in open-access papers, as found by Europe PMC text mining. Sharing a sentence is not in itself a finding about the gene and the disease. The quoted sentences say what the papers report.
atherosclerosis (159 papers, 2007 to 2025). A disease characterized by the build-up of fatty material and calcium deposition in the arterial wall resulting in partial or complete occlusion of the arterial lumen. "Deficiency of ABCA1 and ABCG1 in macrophages increases inflammation and accelerates atherosclerosis." (PMID 41252867, 2025). "Meanwhile, combined Abca1 and Abcg1 deficiency promotes fat cell accumulation and accelerates the development of atherosclerosis in mice." (PMID 39857239, 2024). "In contrast to Abcg1 deficiency in macrophages, loss Abcg1 in T cells and in particular Tregs has been found to be protective against atherosclerosis progression." (PMID 39088185, 2024). "Atherosclerosis progression studies in Abcg1−/− mice have been mixed, a comprehensive review of atherosclerosis studies in Abcg1−/− mice on an LDL−/− background shows that in mice loss of Abcg1 in early lesions leads to enhanced progression." (PMID 39088185, 2024). "Taken together this would suggest that loss of Abcg1 in our current study would be expected to result in a pro-inflammatory macrophage phenotype and decreased atherosclerosis regression." (PMID 39088185, 2024). "Genetic polymorphisms within ABCA1 or ABCG1 have been associated with susceptibility to atherosclerosis." (PMID 38474781, 2024). "Increased SMAD1 expression leads to decreased levels of the cholesterol transporters ABCA1 and ABCG1, with lipid accumulation by macrophages producing foam cells that are associated with atherosclerosis." (PMID 37164635, 2023). "ABCA1 and ABCG1 deficiency increases foam cell formation and accelerates the development of atherosclerosis in mice." (PMID 37324843, 2023). "The excess cholesterol in macrophages can also be excreted by the ATP-binding cassette subfamily A member 1 (ABCA1) or subfamily G member 1 (ABCG1) which prevents the formation of foam cells thereby reducing the risk of atherosclerosis and CVD." (PMID 36159325, 2022). "Another switch gene associated with low physical activity, ABCG1, is a cholesterol transporter that helps prevent the formation of high-density lipoprotein and atherosclerosis." (PMID 35682902, 2022). "Mice deficient in ABCA1 and ABCG1 display leukocytosis, increased proliferation of hematopoietic stem and multipotential progenitor cells in the bone marrow, and accelerated atherosclerosis." (PMID 35052806, 2022). "ABCA1 and ABCG1 have been linked to atherosclerosis, and their potential substrates besides cholesterol include phospholipids as well as oxysterols." (PMID 31159502, 2019). "In cases where mouse peritoneal macrophages were loaded with high cholesterol, ABCA1 and ABCG1 expression was enhanced while combined deficiency of both receptors resulted in foam cells accumulation and atherosclerosis." (PMID 29113088, 2017). "It has also been reported that ABCA1 and ABCG1 deficiency in macrophages increases inflammation and accelerates atherosclerosis in mice." (PMID 29137283, 2017). "ABC transporters are particularly relevant for macrophages, since combined deficiency of ABCA1 and ABCG1 promotes foam cells accumulation and accelerates atherosclerosis, and also impairs macrophage migration." (PMID 27545843, 2016).
atherosclerosis (continued). "Recent genetic association studies in humans identified functional variants in ABCG1 associated with increased risk of coronary artery disease, supporting an important role of ABCG1 in atherosclerosis development and cardiovascular disease." (PMID 23826352, 2013). "Excess cholesterol ester production via ACAT1 and decreased cellular cholesterol efflux via ABCG1 are two pathways that may contribute to atherosclerosis caused by Pg-LPS." (PMID 38532421, 2024). "In addition, ABCG1 polymorphisms have been shown to be associated with the risk of atherosclerosis and its clinical manifestations." (PMID 39857239, 2024). "Several other TG-affected genes showed weaker associations with atherosclerosis-related outcomes (ABCG1, AC004791.2, CPA3, CYP11A1, SLC12A3) or rheumatoid arthritis (GATA2, SMPDL3A) but were no longer statistically significant after correction for multiple testing (PFDR > 0.05)." (PMID 36725846, 2023). "Moreover, combined deficiency of ABCA1 and ABCG1 promotes foam cell accumulation and accelerates atherosclerosis in mice." (PMID 36713845, 2023). "Similarly, mice deficient in ABCA1 and ABCG1 specifically in endothelial cells demonstrate decreased eNOS activity, increased endothelial inflammation, and accelerated atherosclerosis." (PMID 35052806, 2022). "Targeting ABCG1 has been suggested to reduce the risk of atherosclerosis and AD." (PMID 35682902, 2022). "Mice doubly deficient in Abca1 and Abcg1 exhibit worsened atherosclerosis." (PMID 35714730, 2022). "On the contrary, mice deficient in ABCA1 and ABCG1 accelerate atherosclerosis." (PMID 34026849, 2021). "M2-polarizing diabetic macrophages markedly induced SR-A, SR-B1, and ABCG1, which could be responsible for diabetes-associated pathogenesis of atherosclerosis and inflammation." (PMID 32640667, 2020). "Loss of Abcg1 in endothelial cells was shown to accelerate mechanisms of atherosclerosis, such as increased monocyte-endothelial cell adhesion, and in the presence of HDL, eNOS uncoupling and nitric oxide synthesis through interactions of eNOS and caveolin-1 at the membrane." (PMID 30087224, 2018). "Taken together, a large body of evidence suggests that Abcg1 could play a role in diabetes as well as in accelerated atherosclerosis associated to diabetes through modulation of insulin secretion and foam cell formation, respectively." (PMID 28869506, 2017). "In addition, Abcg1 deficiency in mice under high-fat and high-cholesterol feeding was either protective or deleterious against atherosclerosis in wild-type mice or in Apoe−/− mice, respectively." (PMID 28869506, 2017). "The overall aim of the work was to provide functional evidence for the correlation of rs57137919 with atherosclerosis and ascertain whether the ABCG1 promoter SNP would result in any phenotypic polymorphisms caused by the alteration in molecular levels." (PMID 24972087, 2014). "The role of the cholesterol transporters ABCA1, ABCG1 and SR-BI in macrophage cholesterol efflux has been extensively studied, and it has been shown that impaired cellular cholesterol efflux is associated with atherosclerosis in humans." (PMID 25181357, 2014). "In conclusion, through the use of human PBMC-derived macrophages as well as various cell lines, this study has shown that a promoter SNP in ABCG1 is functionally interrelated with the gene expression and apoptosis of macrophages, leading to a phenotypic difference and a cause for atherosclerosis." (PMID 24972087, 2014). "Using this complex knock-out mouse we show that loss of Abcg1 leads to the expected reduction in cholesterol efflux to HDL but that this did not impact circulating cholesterol levels or plaque area in either a progressive or regressive atherosclerosis environment." (PMID 39088185, 2024). "Capsaicin promotes cholesterol efflux via upregulation of the expression of ABCA1 and ABCG1 in macrophages of atherosclerosis." (PMID 39809738, 2025).
atherosclerosis (continued). "Further, it suggests that USP18 knockdown encourages foam cell formation and expedites atherosclerosis progression by enhancing ABCG1 degradation." (PMID 39804798, 2025). "As expected, cholesterol transporters, ABCA1 and ABCG1, are also important targets through which foamy macrophages influence atherosclerosis progression." (PMID 40384967, 2025). "A recent study has shown that YXTMD, a traditional Chinese decoction, effectively increases cholesterol efflux by activating PPARγ-LXR-ABCA1/ABCG1 pathway in foamy macrophages and attenuates atherosclerosis in Apoe−/− mice." (PMID 40384967, 2025). "In summary, our results suggested that USP18 plays a crucial role in managing the progression of atherosclerosis by strengthening the expression of ABCG1 protein through its deubiquitinating effect on ABCG1." (PMID 39804798, 2025). "The impaired molecular machinery we observed—including reduced expression of receptors (Scarb1) and transporters (Abca1, Abcg1)—strongly suggests a functional deficit in the lymphatic RCT pathway in advanced atherosclerosis." (PMID 41465071, 2025). "Increased pathways involved in lipids and atherosclerosis likely relate to the formation of foam cells (e.g. genes Olr1, Abca1, and Abcg1)." (PMID 40513100, 2025). "ABCA1 and ABCG1 transporters are potential pharmacological targets for the prevention and treatment of atherosclerosis." (PMID 41300518, 2025). "ABCG1, a member of the adenosine triphosphate binding cassette family, has predominantly been researched within the contexts of atherosclerosis 21, diabetes, and tumor resistance." (PMID 40520894, 2025). "Considering the pivotal role of metabolic imbalance in cholesterol as a constituent cause of atherosclerosis, we investigated the concentrations of proteins affiliated with cholesterol absorption and discharge, inclusive of CD36, SR‐A1, ABCA1, and ABCG1." (PMID 39804798, 2025). "Abnormal expression of ABCG1 affecting lipid metabolism and is involved in pathogenesis and progression of diverse diseases such as atherosclerosis, Alzheimer's disease, impairment in glucose tolerant and diabetes." (PMID 38896016, 2024). "Studies related to genetics in humans discovered various functions of ABCG1 associated with increased risk of CAD, revealing a notable role of ABCG1 in protecting from atherosclerosis and CVD." (PMID 38474781, 2024). "Patients with atherosclerosis have been shown to have significantly reduced ABCG1 levels in circulating peripheral blood mononuclear cells." (PMID 39088185, 2024). "In macrophages, ABCG1 helps remove excess cholesterol in HDLs, preventing macrophages from turning into foam cells, a key step in the development of atherosclerosis." (PMID 39857239, 2024). "In macrophages, the upregulated expression of ABCG1 mediates cholesterol efflux and links HDL levels to atherosclerosis risk." (PMID 38896016, 2024). "In order to investigate the role of Abcg1 in atherosclerosis progression and regression, Abcg1+/+ and Abcg1−/− mice on the REVERSA background were fed a high fat diet for three months from 4 to 16 weeks of age to induce atheroma." (PMID 39088185, 2024). "Several studies have shown that lower levels of ABCG1 mRNA and ABCG1 protein were found in macrophages from patients with atherosclerosis." (PMID 39857239, 2024). "In order to compare atherosclerosis progression between Abcg1+/+ and Abcg1−/− mice, a cohort of mice were harvested at 16 weeks prior to regression." (PMID 39088185, 2024). "In this regard, ATP-binding cassette transporters (such as ABCA1 and ABCG1) mediate cholesterol efflux from macrophages, thus limiting the formation of foam cell and atherosclerosis." (PMID 39424784, 2024). "From this data it is clear to see that Abcg1 has multiple contrasting roles in atherosclerosis which taken together along with our findings indicate that Abcg1 is not a rational target in atherosclerosis progression or regression." (PMID 39088185, 2024).